TRPM4 (transient receptor potential cation channel subfamily M member 4)
Diseases named in the same sentence as TRPM4 in open-access papers (continued):
Sharing a sentence is not in itself a finding about the gene and the disease.
Stroke (continued). "As TRPM4 upregulation occurs at 2 h post-stroke induction, a transient stroke model was created in rats by occluding the middle cerebral artery for 2 h and reperfusion was achieved by removing the luminal thread." (PMID 29569041, 2019). "Again, TRPM4 siRNA treatment significantly reduced hemorrhage at 1 day following stroke reperfusion." (PMID 29569041, 2019). "TRPM4 upregulation in vascular endothelium has previously been reported in animal models of spinal cord injury and stroke, as well as in human stroke post-mortem brains." (PMID 29569041, 2019). "To further investigate how TRPM4 inhibition affects BBB integrity following stroke, we examined the expression of tight junction (TJ)-related proteins in brain tissues surrounding the infarct using microarray." (PMID 29569041, 2019). "For comparison, at 2 h post-stroke, 50.6 ± 4.1% vWF-positive vessels were co-stained by anti-TRPM4 antibody which increased to 72.6 ± 3.4% by 6 h." (PMID 29569041, 2019). "When we examined the blood vessels in the hyperacute phase of stroke, it was revealed that 2 h after stroke induction, TRPM4 upregulation was clearly identified in vessels surrounding infarct core." (PMID 29569041, 2019). "Recently, TRPM4 has emerged as a therapeutic target for many brain disorders such as stroke, spinal cord injury, and head injury." (PMID 31664513, 2019). "The differential expression of TRPM4 in endothelium and neurons at early stage of stroke suggests that the effect of hypoxia is heterogeneous among various cells and locations." (PMID 29569041, 2019). "In our previous study using a permanent stroke model, TRPM4 blockade has been shown to temporarily improve motor functions." (PMID 29569041, 2019). "In conclusion, we have developed a TRPM4-specific blocking antibody that can alleviate stroke injury during reperfusion." (PMID 31664513, 2019). "Recently, transient receptor potential melastatin 4 (TRPM4) channel has emerged as a potential target for vascular protection in stroke management." (PMID 31664513, 2019). "In the present study, we identified that TRPM4 channel was upregulated as early as 2 h post-stroke induction." (PMID 29569041, 2019). "Our results showed that M4P accumulated inside the vessels within the infarct area, possibly via collateral circulation, and bind to the endothelial TRPM4 where the channel is upregulated as early as 2 h after stroke." (PMID 31664513, 2019). "At 6 h post-stroke, more blood vessels including smaller ones were positively stained by anti-TRPM4 antibody." (PMID 29569041, 2019). "We have found that TRPM4 siRNA could suppress TRPM4 expression only within the ipsilateral hemisphere in both permanent and transient stroke models." (PMID 37380823, 2023). "Endothelial upregulation of TRPM4 occurs as early as 2 h post‐stroke induction." (PMID 36527242, 2023). "Interestingly, the expression pattern of TRPM4 in neurons after stroke is also similar as SLC26A11, mainly located within the surviving tissue close to the infarct core." (PMID 37380823, 2023). "We hypothesize that TRPM4 blocking antibody could reduce delayed stroke reperfusion injury and possibly extend the time window of current reperfusion therapy." (PMID 37239151, 2023). "Stroke also upregulates TRPM4 expression in the vascular endothelium." (PMID 36527242, 2023). "Several TRPM channels, such as TRPM2, TRPM4, and TRPM7 have been implicated in stroke." (PMID 36527242, 2023). "Under hypoxic conditions such as stroke, TRPM4 activity is greatly enhanced." (PMID 37239151, 2023). "Using a polypeptide from rat TRPM4, we have generated a polyclonal antibody M4P which could alleviate reperfusion injury in a rat model of stroke." (PMID 34002002, 2021). "The differential expression of TRPM4 after stroke has been reported previously in an animal model." (PMID 34002002, 2021). "TRPM4 is a calcium-activated non-selective monovalent cation channel implicated in diseases such as stroke." (PMID 34002002, 2021).
Stroke (continued). "As in vitro studies showed that M4M and M4M1 could only bind to human TRPM4, we employed western blot on tissues harvested from the rat stroke brains." (PMID 34002002, 2021). "During the acute stage of stroke, blocking TRPM4 channel could protect neurons and vascular endothelial cells from oncotic cell death." (PMID 33195194, 2020). "Both TRPM4 expression and activity are enhanced after stroke." (PMID 33195194, 2020). "Our results support the use of TRPM4 blocker for early stroke reperfusion." (PMID 29569041, 2019). "The results from both in vitro data using cultured cells and in vivo data in stroke model indicated that M4P application could inhibit the expression of TRPM4." (PMID 31664513, 2019). "The reduction in tissue damage, measured by TTC staining, T2-weighted MRI, and [18F]FDG-PET imaging was very consistent (around 30%), strongly suggesting that TRPM4 inhibition in this transient stroke model could salvage significant amounts of brain tissue." (PMID 29569041, 2019). "In this transient stroke model, TRPM4 suppression again greatly improved vascular morphology." (PMID 29569041, 2019). "TRPM4 channel has been shown to be upregulated in neurons after stroke." (PMID 31664513, 2019). "Vascular fragmentation, a sign of vascular damage, appeared after 1 day in a permanent stroke model and could be rescued by TRPM4 inhibition." (PMID 29569041, 2019). "Our results demonstrate that TRPM4 blockade could attenuate reperfusion injury in stroke recanalization." (PMID 31664513, 2019). "The present study was undertaken to develop a novel TRPM4 blocker for stroke management." (PMID 31664513, 2019). "In this study, we describe the production of a TRPM4-specific blocking antibody M4P and demonstrate that M4P could improve stroke outcome in stroke reperfusion model." (PMID 31664513, 2019). "TRPM4 upregulation in endothelium emerges as early as 2 h post-stroke induction." (PMID 29569041, 2019). "As TRPM4 expression in cerebral vasculature is upregulated as early as 2 h after stroke induction, we hypothesise that M4P application could reduce reperfusion injury during early phase of stroke." (PMID 31664513, 2019). "TRPM4 upregulation was also identified in cortical neurons close to infarct 6 h post-stroke." (PMID 29569041, 2019). "However, much less is known regarding the suppression of TRPM4 expression in live animals in stroke, in particular, after ischemia reperfusion." (PMID 29569041, 2019). "However, there is controversy regarding the regulatory role of SUR1 on TRPM4 and the effect of sulfonylureas in stroke treatment." (PMID 29569041, 2019). "TRPM4 upregulation has been reported in both permanent and transient stroke models." (PMID 31664513, 2019). "To examine whether M4P could bind to TRPM4 channels in cerebral vasculature in stroke, we injected 100 μg of M4P, control rabbit IgG, or a vehicle solution intravenously into rats 2 h after stroke induction." (PMID 31664513, 2019). "Therefore, TRPM4 has become a potential target for stroke management." (PMID 33195194, 2020). "Therefore, our data indicate that the expression of claudin-1 and claudin-2 may be a result from TRPM4 suppression after stroke." (PMID 29569041, 2019). "Besides stroke therapy, M4P can serve as a research tool to study TRPM4 channel." (PMID 31664513, 2019). "A future humanised TRPM4 blocking antibody could be a potential therapy for stroke in humans." (PMID 31664513, 2019). "In an animal model of stroke reperfusion, MRI and PET scans show that TRPM4 inhibition by siRNA resulted in a drastic reduction of cerebral edema and infarction." (PMID 37239151, 2023). "Finally, given that ongoing clinical trials specifically targeting TRPM4 have been approved in patients with stroke, it can be expected that, soon, other TRP-based therapeutic strategies may have an adequate safety profile and be applied in the field of cancer, including haematological malignancies." (PMID 34065398, 2021).
Stroke (continued). "Western blot further proves that in vivo TRPM4 siRNA was able to inhibit TRPM4 expression in this transient MCAO model, similar to what we observed in a permanent stroke model." (PMID 29569041, 2019). "In our past studies using siRNA or M4P to inhibit TRPM4 in stroke animal models, we did not encounter any side effect on the functions of vital organs." (PMID 34002002, 2021). "TRPM4 is an ideal target for stroke treatment as it is not expressed in brain tissue; thus, blockade of TRPM4 is unlikely to affect normal brain functions." (PMID 29569041, 2019). "TRPM4 has been reported to form a channel complex with sulfonylurea receptor-1 (SUR1), an auxiliary subunit of KATP channel, and SUR1 blocker sulfonylureas have been used to treat brain diseases such as stroke." (PMID 29569041, 2019). "Therefore, the application of TRPM4 siRNA beyond 2 h following stroke onset is unlikely to achieve optimal outcomes." (PMID 37239151, 2023). "However, as M4M could not block rodent TRPM4, no therapeutic effect was observed in a stroke model using wild type rats." (PMID 34002002, 2021).
Arrhythmia (22 papers, 2014 to 2024). Any cardiac rhythm other than the normal sinus rhythm. "Although variants in TRPM4 have been associated with arrythmias, our case, with the p.Arg905Trp variant, demonstrated recurrent EHI that was found to be complicated by syncope and which was diagnosed as MH susceptible, with no variants in MH candidate genes." (PMID 39457051, 2024). "Our results are especially important in the light of recent findings identifying TRPM4 as a promising drug target in cardiac arrhythmias especially because it has been shown that this type of arrhythmia is often associated with seizures." (PMID 37101159, 2023). "It was often found that the same genotype variant of TRPM4 produces multiple phenotypes of arrhythmias while its multiple genotype mutations cause an arrhythmia with similar clinical features." (PMID 37511555, 2023). "Human TRPM4 (hTRPM4) is among the most important cardiac TRP channels whose pathogenic variants are associated with cardiac arrhythmias." (PMID 38100498, 2023). "The TRPM4 channel likely contributes to the development of cardiac arrhythmias associated with specific genetic backgrounds and cardiac remodeling." (PMID 37511555, 2023). "The aim of our study was to elucidate the interactions between aldosterone and TRPM4 in atrial remodeling and arrhythmias susceptibility." (PMID 33809210, 2021). "Due to its wide distribution, TRPM4 dysfunction has been linked with several pathophysiological processes, including inherited cardiac arrhythmias." (PMID 33381229, 2020). "In the heart, TRPM4 has been associated with different forms of inherited cardiac arrhythmias through the identification of many pathogenic genetic variants in the affected patients." (PMID 33381229, 2020). "Taken together, we provide evidence that overexpression of TRPM4 increases the susceptibility of living mice to stress-induced arrhythmias." (PMID 31316392, 2019). "The role of TRPM4 in cardiac fibroblasts has not been evaluated, although TRPM4 channel function has been shown to be essential for cardiac conduction, and the dysfunction of TRPM4 is associated with conduction defects and arrhythmia." (PMID 31547577, 2019). "Taken together, our data provide the first evidence in a living animal that increased expression of TRPM4 is sufficient to increase the risk of stress-induced arrhythmias." (PMID 31316392, 2019). "In this study, we provide evidence that overexpression of TRPM4 is sufficient to increase the susceptibility of a living mouse to cardiac arrhythmias." (PMID 31316392, 2019). "TRPM4 channel has also been implicated at the ventricular level, in inotropism or in arrhythmia genesis due to stresses such as ß-adrenergic stimulation, ischemia-reperfusion, and hypoxia re-oxygenation." (PMID 25531103, 2014). "Such altered PIP2 interaction may provide a novel pathogenic mechanism underlying TRPM4 channelopathies including arrhythmias." (PMID 33922380, 2021). "In this study, we have tested whether increased expression of wild-type (WT) TRPM4 augments the risk of arrhythmias in living mice." (PMID 31316392, 2019). "The TRPM4 inhibitor, 9-phenanthrene, has been demonstrated to effectively mitigate arrhythmias induced by ventricular hypoxia and reoxygenation in mice." (PMID 39726787, 2024). "Ectopic activation patterns indicate a participation of PFs in these arrhythmias, with a potential involvement of TRPM4 channels, shown by the reduction of arrhythmias by 9-Phenanthrol." (PMID 36814643, 2023). "For instance, Ca2+ overload and ATP depletion increase the activity of the TRPM4 cation channel, which has been implicated in fatal CIR-induced arrhythmias." (PMID 36975867, 2023). "This short review aims to overview what is known so far about the TRPM4 channel in cardiac electrophysiology and arrhythmogenesis, highlighting its potential as a novel therapeutic target to effectively prevent and treat cardiac arrhythmias." (PMID 37511555, 2023).
Arrhythmia (continued). "Different kinds of inherited cardiac arrhythmias, including conduction blocks, Brugada syndrome (BrS), and long QT syndrome (LQTS), have been linked to dozens of Trpm4 gene mutations, as evidenced by genetic linkage analyses and subsequent cohort studies." (PMID 37511555, 2023). "In these conditions 45% (N = 11) of atria from Trpm4+/+-CTRL mice and 58% (N = 12) of atria from Trpm4+/+-AL+S exhibited arrhythmias (N = 11)." (PMID 33809210, 2021). "On Trpm4-/- mice, arrhythmias were detected in 78% (N = 9) of atria from Trpm4-/--CTRL but 33% (N = 9) after aldosterone + salt treatment." (PMID 33809210, 2021). "When evaluating the number of arrhythmias for periods of 15 min, it appeared a significantly higher number of arrhythmias in Trpm4-/--CTRL mice compared to Trpm4+/+-CTRL." (PMID 33809210, 2021). "Cardiac arrhythmias are indeed associated with TRPM4, as early afterdepolarization (EAD) was dose-dependently reduced by TRPM4 inhibition in mice." (PMID 34502410, 2021). "Although the different stages that involved the TRPM4 channel in the effects of aldosterone remain to be determined, our data provide new arguments indicating that TRPM4 is a major target in cardiac arrhythmias." (PMID 33809210, 2021). "The present review discusses the pathophysiological implications of TRPM4 dysfunction in inherited cardiac arrhythmias, especially inherited cardiac conduction disorders, Brugada syndrome, and the congenital long QT syndrome." (PMID 33381229, 2020). "Clearly, mice with the strongest arrhythmias are found in the group with moderate to strong overexpression of TRPM4." (PMID 31316392, 2019). "The link between TRPM4 and arrhythmia, wherein 9-phenanthrol can inhibit TRPM4 and can shorten the duration of action potentials (APs), has been confirmed previously, which implies that TRPM4 can delay AP repolarization." (PMID 29914130, 2018). "Several lines of evidence suggest that TRPM4 is closely related to arrhythmias." (PMID 39726787, 2024). "In cardiac electrophysiology, TRPM4 channels influence membrane potential to alter excitability through participation in membrane voltage regulation of intracellular Ca2+, which is closely related to arrhythmias." (PMID 39726787, 2024). "Alternatively TRPM-4 blockade may affect electrical activity by a generic decrease in excitability which increases the threshold for the triggering and/or sustaining of arrhythmias." (PMID 36814643, 2023). "We tested whether PFs and specifically TRPM4 channels, play a role in these mechanically-induced arrhythmias." (PMID 36814643, 2023). "Interestingly, an in vivo study of a mouse model, where acute ischemia was induced by ligation of the left anterior descending (LAD) coronary artery for 30 min, showed that Trpm4 KO mice are much less likely to develop ischemia-induced arrhythmias." (PMID 37511555, 2023). "Previous studies reported that the TRPM4 current contributes to the mammalian atrial action potential as well as to the notch and early repolarisation phases of the action potential in Purkinje cells, providing a potential link to cardiac arrhythmias." (PMID 34190686, 2021). "Based on these, it seems that the native TRPM4 current might contribute to cardiac arrhythmia, in agreement with previous studies." (PMID 34502410, 2021). "We thus hypothesized that the effect of aldosterone could involve TRPM4 for morphological modifications as well as electrical perturbations leading to atrial arrythmias." (PMID 33809210, 2021). "Further research will need to clarify the precise mechanism, and establish whether blockade of TRPM4 prevents or suppresses arrhythmias." (PMID 31316392, 2019). "TRPM4 inhibition with 9-phenanthrol also mimicked the reduction of action potential duration evoked by TRPM4 deletion in atrial cells and reverted the early after-depolarization involved in cardiac arrhythmias observed after a process of hypoxia and re-oxygenation." (PMID 30881310, 2019).
Arrhythmia (continued). "Moreover, TRPM4 also plays an important role in the development of cardiomyocytes and multiple cardiovascular diseases, including endothelial injury, myocardial ischemia, myocardial hypertrophy, arrhythmias, heart failure, etc." (PMID 39726787, 2024). "The number of arrhythmias was reduced by aldosterone + salt treatment in Trpm4-/- animals while not reaching significance." (PMID 33809210, 2021). "In experiments on Trpm4-/- mice, arrhythmias were detected even in the absence of aldosterone treatment, in 80% of atria (N = 10) and in 44% (N = 9) after aldosterone treatment which is not significantly different." (PMID 33809210, 2021). "Altogether, these data suggest that the absence of TRPM4 slows electrical conduction, favoring the generation of arrhythmias in part through the dysregulation of the cardiac autonomic nervous system." (PMID 25531103, 2014). "None of the atria from Trpm4+/+-CTRL mice exhibited arrhythmias (N = 11)." (PMID 33809210, 2021).